FAM20C (FAM20C golgi associated secretory pathway kinase)
Description:
Golgi serine/threonine protein kinase that phosphorylates secretory pathway proteins within Ser-x-Glu/pSer motifs and plays a key role in biomineralization of bones and teeth. Constitutes the main protein kinase for extracellular proteins, generating the majority of the extracellular phosphoproteome. Mainly phosphorylates proteins within the Ser-x-Glu/pSer motif, but also displays a broader substrate specificity. Phosphorylates ERO1A, enhancing its activity which is required to maintain endoplasmic reticulum redox homeostasis and for oxidative protein folding. During endoplasmic reticulum stress, phosphorylates P4HB/PDIA1 which induces a functional switch, causing P4HB to change from an oxidoreductase to a molecular chaperone. This is critical to maintain ER proteostasis and reduce cell death under ER stress. Phosphorylation of P4HB also promotes its interaction with ERN1, leading to reduced activity of ERN1, a key sensor for the endoplasmic reticulum unfolded protein response. Required for osteoblast differentiation and mineralization. Phosphorylates casein as well as a number of proteins involved in biomineralization such as AMELX, AMTN, ENAM and SPP1/OPN. In addition to its role in biomineralization, also plays a role in lipid homeostasis, wound healing and cell migration and adhesion.
Synonyms: DMP-4; GEF-CK; DMP4; IMAGE:4942737; DKFZp547D065; G-CK; RNS
Tractability: Small molecule: a structure with a bound ligand is known. Antibody: UniProt places it where antibodies can reach, with high confidence; UniProt predicts a signal peptide or a membrane-spanning region; its Gene Ontology location is reachable by antibodies, with medium confidence. PROTAC: its protein half-life has been measured; a small molecule that binds it is known.
Target class: Enzyme; Transferase
Gene: Protein-coding gene on chromosome 7 (192,034 to 260,772, forward strand). Ensembl gene ENSG00000177706.
Subcellular location: Golgi apparatus membrane; Secreted; Endoplasmic reticulum
Subcellular location (Human Protein Atlas): Golgi apparatus; Nucleoplasm; Predicted to be secreted
Pathways (Reactome):
Metabolism of proteins: Post-translational protein phosphorylation; Regulation of Insulin-like Growth Factor (IGF) transport and uptake by Insulin-like Growth Factor Binding Proteins (IGFBPs)
Gene Ontology:
Molecular function: manganese ion binding; protease binding; protein binding; protein kinase activity; protein serine kinase activity; protein serine/threonine kinase activity; calcium ion binding
Biological process: biomineral tissue development; protein phosphorylation; enamel mineralization; post-translational protein modification
Cellular component: endoplasmic reticulum; extracellular exosome; extracellular region; Golgi apparatus; Golgi membrane; endoplasmic reticulum lumen; cytoplasm
Genetic constraint (gnomAD): Loss-of-function variants: 41 observed, 43.38 expected, observed/expected ratio (o/e) 0.95, 90% interval 0.74 to 1.23. The synonymous counts are far from expectation, so gnomAD's model fits this gene poorly and the ratio says little. Missense variants: 861 observed, 737.27 expected, observed/expected ratio (o/e) 1.17, 90% interval 1.1 to 1.24. Synonymous variants: 406 observed, 326.03 expected, observed/expected ratio (o/e) 1.25, 90% interval 1.15 to 1.35.
Gene-disease validity (ClinGen):
ClinGen rates the evidence that FAM20C causes each of these diseases.
lethal osteosclerotic bone dysplasia (autosomal recessive): Definitive. Generalized osteosclerosis with periosteal bone formation, characteristic facial dysmorphism, brain abnormalities including intracerebral calcifications, and neonatal lethal course.
Homologues: Orthologues: macaque FAM20C (97% identical), pig FAM20C (90% identical), mouse Fam20c (86% identical), rat Fam20c (86% identical), dog FAM20C (79% identical), guinea pig FAM20C (73% identical), tropical clawed frog fam20c (71% identical), zebrafish fam20cb (69% identical), zebrafish fam20ca (67% identical), Drosophila melanogaster CG31145 (42% identical), Caenorhabditis elegans famk-1 (30% identical). Paralogues in human: FAM20A (42% identical), FAM20B (27% identical).
Diseases named in the same sentence as FAM20C in open-access papers:
FAM20C is named in the same sentence as 96 diseases in open-access papers, as found by Europe PMC text mining. Sharing a sentence is not in itself a finding about the gene and the disease. The quoted sentences say what the papers report.
Raine syndrome (36 papers, 2011 to 2026). "Its physiological importance is highlighted by Raine syndrome, a rare, autosomal recessive disorder caused by FAM20C loss-of-function mutations, characterized by defective bone mineralization that can lead to early death in its most severe form." (PMID 41301500, 2025). "It is known that Raine syndrome is caused by a mutation in the family with sequence similarity 20, member C (FAM20C) gene." (PMID 37180977, 2023). "Raine syndrome (MIM #259775) is an autosomal recessive disorder caused by a mutation in the FAM20C gene." (PMID 37180977, 2023). "At the physiological and pathological level, FAM20C gene mutations or aberrant function of kinase lead to many diseases, such as Rains Syndrome, cancers, and other diseases." (PMID 37370126, 2023). "Expression of known Raine syndrome mutations of FAM20C in an osteosarcoma cell line showed that these mutations reduced FAM20C kinase activity and, in some cases, its secretion." (PMID 36912485, 2023). "In Raine syndrome, all the observed phenotypic modifications are caused by mutations in the FAM20C gene." (PMID 37180977, 2023). "A lethal sclerosing bone dysplasia, Raine syndrome, is an autosomal recessive disorder caused by mutations in FAM20C, one of the three related proteins constituting a “family with sequence similarity 20, members A–C”1–5." (PMID 36572689, 2022). "We conclude that XYLK activity-dependent GAG biosynthesis is essentially unaffected by Raine syndrome mutations in FAM20C." (PMID 36572689, 2022). "Bi-allelic mutations in FAM20C gene are known to cause a rare genetic disorder- Raine syndrome (RS)." (PMID 33676444, 2021). "Although Fam20C was not considered as a kinase located in Golgi apparatus at the beginning, genetic screen demonstrated that Fam20C was the causative gene for Raine’s syndrome, a rare lethal osteosclerosis bone dysplasia in humans reported at 1989." (PMID 33942849, 2021). "Compared with the abrogation or decreased Fam20C activity in Raine’s syndrome and hypophosphatemia rickets, the increased Fam20C expression detected in the variety of cancers implicated that the increased Fam20C activity was more detrimental to the cells." (PMID 33942849, 2021). "Fam20C, a typical member of Fam20 family, has been well-known as a Golgi casein kinase, which is closely associated with Raine Syndrome (RS)." (PMID 34988120, 2021). "Over 40 cases of Raine syndrome have been reported worldwide and DNA sequencing revealed that all these patients carried various alterations in the Fam20C gene, which are likely the driving cause of disease." (PMID 33759783, 2021). "FAM20C mutations are the cause of Raine syndrome (RS) (OMIM # 259775), an autosomal recessive lethal disease characterized by generalized osteosclerosis with periosteal bone formation, characteristic facial dysmorphisms and intracerebral calcifications." (PMID 34360805, 2021). "Variants in the ZFYVE26 gene have been associated with colorectal cancer, variants in the MADCAM1 gene have been associated with multiple sclerosis, and variants in the FAM20C gene have been associated with development of Raine syndrome in humans." (PMID 33195511, 2020). "Raine syndrome (RS) – an extremely rare autosomal recessive genetic disorder, is caused by a biallelic mutation in the FAM20C gene." (PMID 29751744, 2018). "Inactivating mutations in the human FAM20C gene cause Raine syndrome, an autosomal recessive disorder that demonstrates a variety of manifestations." (PMID 28620244, 2017). "FAM20C mutations in humans cause Raine syndrome and our previous studies showed that global inactivation of mouse Fam20C led to bone and dental defects." (PMID 28620244, 2017). "Defects in FAM20C have been associated with a rare human disease, Raine syndrome/FGF23-related hypophosphatemia characterized by dental and bone hypomineralization." (PMID 27187611, 2016). "Mutations in the SCARF2 and FAM20C genes have been associated with the human van den Ende-Gupta and Raine syndromes." (PMID 27187611, 2016).
Raine syndrome (continued). "Our results indicated a causative variant in the kinase domain of FAM20C and established a canine model for human Raine syndrome." (PMID 27187611, 2016). "Among these genes, FAM20A mutations are associated with Amelogenesis Imperfecta (AI) with gingival hyperplasia and nephrocalcinosis, while FAM20C mutations cause Raine syndrome, exhibiting bone and craniofacial/dental abnormalities." (PMID 27292199, 2016). "Mutations in SCARF2 and FAM20C have been associated with the human van den Ende-Gupta and Raine syndromes that include numerous features similar to the affected dogs." (PMID 27187611, 2016). "Mutations in FAM20C cause Raine syndrome, and given the overlap between this condition and the phenotype observed in family 1, this variant was investigated further." (PMID 25928877, 2015). "Intracranial, renal and ectopic gingival calcifications were observed in both of the families described here, suggesting that this finding is a consistent component of Raine syndrome due to FAM20C mutations." (PMID 25928877, 2015). "Participant 237 is a 21-month-old male who was large for age and showed a gain at 7p22.3 which includes the FAM20C gene associated with Raine syndrome." (PMID 25400949, 2014). "Raine syndrome is caused by mutations in FAM20C, which had been reported to encode a secreted component of bone and teeth." (PMID 22900076, 2012). "Genetic studies showed that the loss-of-function mutations in FAM20C were associated with human lethal osteosclerotic bone dysplasia (Raine Syndrome), implying an inhibitory role of this molecule in bone formation." (PMID 22615579, 2012). "FAM20C is highly expressed in the mineralized tissues and identified as the causal gene for lethal osteosclerotic bone dysplasia (Raine Syndrome, OMIM 259775)." (PMID 22615579, 2012). "Raine syndrome is caused by mutations in FAM20C, which has been reported to encode a secreted component of bone and teeth." (PMID 22900076, 2012). "In closing, we discuss the phenotype of fam20b mutant zebrafish with respect to excessive bone formation in Raine syndrome patients, who contain mutations in the paralogous gene FAM20C." (PMID 21901110, 2011). "Renewed focus on Fam20 molecules arose from the revelation that humans with a skeletal disease called Raine syndrome have mutations in FAM20C." (PMID 21901110, 2011). "The non‐lethal manifestation of Raine syndrome caused by FAM20C deficiency presents neurodevelopmental impairment, including developmental delays, intellectual disabilities, hearing loss and seizures, which are exacerbated with the aging and maturation of the central nervous system." (PMID 40511628, 2026). "Raine syndrome is an autosomal recessive disorder caused by FAM20C gene mutations." (PMID 39790934, 2025). "Pathogenic variants of FAM20C gene are the cause of Raine syndrome." (PMID 39790934, 2025). "FAM20C gene variants that are related to Raine syndrome can occur within or outside the kinase activity domain of FAM20C, so it is assumed that abnormal phosphorylation of SIBLINGs resulting from impaired kinase activity promotes the occurrence and development of Raine syndrome." (PMID 39790934, 2025). "Given the critical role of FAM20C in biomineralization and the phosphorylation of secretory proteins, mutations in the FAM20C gene and dysregulation of its kinase activity have been linked to several diseases, including Raine Syndrome (RS), and other pathologies." (PMID 41301500, 2025). "In humans, mutations in the FAM20C gene are responsible for highly lethal Raine syndrome, a neonatal osteosclerotic bone dysplasia (OMIM #259775), characterised by craniofacial anomalies, osteosclerosis and variable hypophosphataemia leading to dental and bone hypomineralisation." (PMID 39559541, 2024). "FAM20C is a member of the Fam20 family known for its association with Raine Syndrome." (PMID 39216004, 2024). "Raine syndrome is a congenital disorder caused by biallelic mutations in the FAM20C gene." (PMID 37180977, 2023).
Raine syndrome (continued). "Since the second child was also diagnosed with Raine syndrome caused by biallelic variations in the FAM20C gene, the family received genetic counseling related to compound heterozygosity and autosomal inheritance pattern to assess the risk of transmission in future pregnancies." (PMID 37180977, 2023). "The variability of phenotype in Raine Syndrome may be produced by changes in the expression of FAM20C protein generated by distinctive pathogenic variants." (PMID 37180977, 2023). "Given that the enzymatic function of FAM20C as an XYLK contributes to Raine syndrome etiology, we expected that mutations in FAM20C would affect its XYLK activity, the phosphorylation status of the Xyl residue in the linkage region, and subsequent GAG production levels." (PMID 36572689, 2022). "Raine syndrome is associated with loss-of-function mutations of FAM20C." (PMID 36572689, 2022). "The kinase-independent actions of FAM20C were most interesting to be explored a potential Raine syndrome etiology because the decreased 4S/6S ratio caused by lethal Raine syndrome mutations in FAM20C was well associated with osteosclerotic status, even in mouse models." (PMID 36572689, 2022). "Given the important role of FAM20C in biomineralization and phosphorylating secretory proteins, mutations of FAM20C gene and aberrant function of fam20c kinase are responsible for many diseases, including Raine Syndrome (RS), cancer, and other diseases." (PMID 34988120, 2021). "Pathogenic variants of FAM20C are responsible for Raine syndrome (RS), initially described as a lethal and congenital osteosclerotic dysplasia characterized by generalized atherosclerosis with periosteal bone formation, characteristic facial dysmorphisms and intracerebral calcifications." (PMID 34360805, 2021). "The broad spectrum of FAM20C functions speculated for different tissues and cells may account for the heterogeneous manifestations of human Raine syndrome caused by FAM20C mutations." (PMID 28620244, 2017). "We identified a novel candidate gene, SLC37A2, for the corresponding human disease, infantile cortical hyperostosis, also known as Caffey disease, and implicated SCARF2 and FAM20C variants in the canine forms of van den Ende-Gupta and Raine syndromes, respectively." (PMID 27187611, 2016). "FAM20C defects cause autosomal recessive osteosclerotic bone dysplasia (Raine syndrome) in humans." (PMID 27187611, 2016). "Interestingly, a mild coagulation defect was incidentally observed during surgery in a patient with Raine syndrome, the autosomal recessive disorder caused by FAM20C mutations, further supporting a possible functional link between FAM20C and coagulation pathways." (PMID 41301500, 2025). "Thus, perturbation of FAM20C interaction with chondroitin 4-O-sulfotransferase-1, as well as loss of kinase activity, may both contribute to the Raine syndrome bone dysplasia phenotypes." (PMID 36912485, 2023). "Genetic alterations in FAM20C compromise mineralisation capacity and disrupt bone mineral homeostasis, as exemplified in Raine syndrome—a pathological condition characterized by osteosclerotic changes and associated developmental abnormalities." (PMID 41207115, 2026). "This cleavage is further regulated via phosphorylation by FAM20C (family with sequence similarity 20, member C, also known as DMP4; the gene mutated in Raine syndrome) and O-glycosylation by GALNT3 (polypeptide N-acetylgalactosaminyltransferase 3)." (PMID 33815294, 2021). "Since the localization of FAM20A was similar to that of FAM20C in tooth, and clinical phenotypes of AI patients with FAM20A mutation partially overlap with those of Raine syndrome patients, we investigated the association of FAM20A with FAM20C." (PMID 27292199, 2016). "Our results identify FAM20C as a kinase for secreted phosphoproteins and establish a biochemical basis for Raine syndrome." (PMID 22900076, 2012).
Raine syndrome (continued). "BACKGROUND: Raine syndrome, RS, (OMIM 259775) is a rare autosomal recessive disorder with prevalence of less than 1:1 000 000, caused by homozygous or compound heterozygous variants in FAM20C gene." (PMID 41896969, 2026). "The recent advances on the phosphoproteome of Fam20C supported the hypothesis that the microenvironment might contribute to the opposite manifestations of Raine’s syndrome." (PMID 33942849, 2021). "These patients may have been arguably the first documented cases of Raine syndrome harboring genetic alterations in Fam20C." (PMID 33759783, 2021). "Furthermore, deletion of FAM20C in whole animals induces a syndrome resembling the human Raine syndrome thus pointing to a function in the extracellular matrix/collagen/Calcium metabolism." (PMID 33499061, 2021). "Some reports showed the presence of periodontitis in non-lethal type of Raine syndrome, where FAM20C is mutated, but genotype–phenotype correlation was not established." (PMID 33051588, 2020). "Although some FAM20C mutations in non-lethal Raine syndrome patients are associated with fibroblast growth factor (FGF) 23-dependent hypophosphatemic rickets or osteomalacia, the mechanisms underlying these contradictory findings in patients and mice models remain elusive." (PMID 36572689, 2022). "Raine syndrome, a lethal osteosclerotic bone dysplasia in humans, is caused by loss-of-function mutations in FAM20C; however, Fam20c deficiency in mice does not recapitulate the human disorder, so the underlying pathoetiological mechanisms remain poorly understood." (PMID 36572689, 2022). "The present study emphasizes the variability of this clinical phenotype, with the further expansion of the clinical and metabolic spectrum of non-lethal Raine Syndrome due to recessive FAM20C mutations, which may both be hypomorphic." (PMID 25928877, 2015). "In fact, a canine model of nonlethal Raine syndrome has been reported exhibiting a minimally disruptive Ala to Val substitution in the Fam20C kinase domain." (PMID 33759783, 2021). "Mice lacking Fam20c present the phenotype similar to human non-lethal Raine syndrome, including growth retardation, rickets/osteomalacia, defects in the growth plate, defective osteocytes differentiation, reduction of serum phosphate, and elevation of serum fibroblast growth factor (FGF23)." (PMID 37370126, 2023).